SNAI1 (snail family transcriptional repressor 1)
Diseases named in the same sentence as SNAI1 in open-access papers (continued):
Sharing a sentence is not in itself a finding about the gene and the disease.
rhabdomyosarcoma (7 papers, 2017 to 2025). A rare aggressive malignant mesenchymal neoplasm arising from skeletal muscle. "Here, we compare three different methods for SNAI1 knockout or knockdown in rhabdomyosarcoma (RMS) cells." (PMID 32354171, 2020). "Rather surprisingly, we find that SNAI1 is highly expressed in rhabdomyosarcoma tumors and that knocking it down reduces self-renewal and growth while elevating tumor differentiation." (PMID 28614716, 2017). "Remarkably, rhabdomyosarcoma cell lines expressing high ICN1 also co-expressed high SNAI1 protein, correlating well with graded gene expression between the two factors." (PMID 28614716, 2017). "In total, our experiments show that the NOTCH1/SNAI1 axis suppresses MEF2C expression, locking cells in a less differentiated cell state while elevating the overall self-renewal potential of rhabdomyosarcoma." (PMID 28614716, 2017). "Gene expression analysis also uncovered a high correlation of SNAI1 and NOTCH1 transcript co-expression in human primary rhabdomyosarcoma (p < 0.0001; Pearson correlation, 0.604)." (PMID 28614716, 2017).
ductal adenocarcinoma (6 papers, 2009 to 2021). "To determine in vivo relevance of our data obtained with cell culture, we utilized our phosphospecific antibody directed against PKD-phosphorylated SNAI1 in tissue microarrays of human normal breast tissue and invasive ductal carcinoma (IDC)." (PMID 22276203, 2012). "Analysis of human tissue samples with a newly-generated phosphospecific antibody for PKD1-phosphorylated SNAI1 showed that regulation of SNAI1 through PKD1 occurs in vivo in normal breast ductal tissue and is decreased or lost in invasive ductal carcinoma." (PMID 22276203, 2012).
leukemia (6 papers, 2018 to 2026). A malignant (clonal) hematologic disorder, involving hematopoietic stem cells and characterized by the presence of primitive or atypical myeloid or lymphoid cells in the bone marrow and the blood. "SNAI1 is a key modulator of epithelial-to-mesenchymal transition (EMT) and has been linked to leukemia pathophysiology by impairing differentiation and enhancing self-renewal and proliferation of blast cells through its interaction with the histone demethylase KDM1A/LSD1." (PMID 41596324, 2026). "Statistically significant differences between the leukemia and MRD-negative groups were achieved by JUP, NT5C3B, MYC, GATA3, PTK7, CNP, SNAI1, and ICOSLG." (PMID 41596324, 2026). "Although SNAI1, ZEB1, and ZEB2 were not upregulated in RNA-seq data of Adh ALL patient samples, they have putative roles in leukemia development/progression, and we observed SNAIL (SNAI1) and ZEB1 but not ZEB2 to be highly expressed in Adh leukemic cell lines." (PMID 37453060, 2023).
atherosclerosis (5 papers, 2021 to 2024). A disease characterized by the build-up of fatty material and calcium deposition in the arterial wall resulting in partial or complete occlusion of the arterial lumen. "Accordingly, endothelial KLF11 deficiency in the diabetic atherosclerosis model increased the binding activities of lipoprotein particles and growth factors and the expression of Notch1 and Snai1." (PMID 39462409, 2024).
colorectal adenocarcinoma (5 papers, 2017 to 2022). The most common type of colorectal carcinoma. "We previously performed a global transcriptomic and phenotypic characteristic of the HT29 colorectal adenocarcinoma cell line affected by the transcription factor Snail (Snai1), a core regulator of the early stages of the epithelial phenotype conversion that initiates metastasis." (PMID 30770873, 2019).
Hyperglycemia (5 papers, 2017 to 2025). An increased concentration of glucose in the blood. "Additionally, we observed interactions involving KRT19, SNAI1, and OCLN that suggest a potential association of hyperglycemia with fibrosis-related pathways in TM." (PMID 39764143, 2024).
mesenchymal tumors (5 papers, 2014 to 2022). "In support of this view, moderate upregulation of Snai1 or Snai2, as induced in CombitTA-Snai1 and CombitTA-Snai2 transgenic mice, is associated with spontaneous development of epithelial and/or mesenchymal tumors." (PMID 24638100, 2014).
neuroblastoma (5 papers, 2016 to 2022). Neuroblastoma (NB) is the most common solid, extracranial childhood tumor. "We assayed markers of both mesenchymal differentiation (VIM, PRRX1 and SNAI1) and adrenergic differentiation (NCAM, NF68), but observed no reproducible changes in gene expression, suggesting that GATA3 knock-down only affects proliferation and death, but not differentiation, in neuroblastoma cells." (PMID 31831790, 2019).
renal cell carcinoma (5 papers, 2013 to 2024). "Interestingly, in renal cell carcinomas (RCC), tECs Snai1 and Slug were downregulated, and Twist1 expression levels barely changed compared to kidney-derived nECs." (PMID 39095583, 2024). "In the present study, we first measured the effect of acetate on zinc finger transcriptional repressor SNAI1 and acetyl-CoA synthetase 2 (ACSS2) under glucose limitation in renal cell carcinoma cell lines, 786-O and ACHN." (PMID 32458971, 2020).
glaucoma (4 papers, 2024 to 2025). Increased pressure in the eyeball due to obstruction of the outflow of aqueous humor. "Targeting pathways involved in oxidative stress and fibrosis, such as TXNIP, SNAI1, and related signaling pathways, can provide new therapeutic approaches in managing elevated IOP and mitigating glaucoma progression in diabetic patients." (PMID 39764143, 2024).
lung squamous cell carcinoma (4 papers, 2019 to 2025). "The SNAI1 gene was disrupted in the HCC95 and NCI H520 cell line using CRISPR technology with sgRNA to assess the prognostic value of SNAI1 in lung squamous cell carcinoma (LUSC)." (PMID 40515636, 2025).
metastatic melanoma (4 papers, 2013 to 2024). A melanoma that has spread from its primary site to another anatomic site. "As for SNAI1, the highest expression was observed in the metastatic melanoma group, without significant differences among groups." (PMID 39273022, 2024). "Results showed the highest SNAI1 mRNA expression in metastatic melanoma, regardless of BRAF status." (PMID 39273022, 2024).
prostate (4 papers, 2014 to 2022). "Increased SNAI1 expression is considered an early event in the progress of prostate carcinogenesis but is limited to cells with invasive properties." (PMID 24565133, 2014). "During prostate carcinogenesis, EMT is related to cancer progression, migration and metastasis, and mesenchymal markers and transcription factors, such as vimentin, N-cadherin, Snai1, and Twist1/2, are highly upregulated." (PMID 34298624, 2021).
breast adenocarcinoma (3 papers, 2017 to 2021). "We crossreferenced and compared the significantly altered RPE-EMT genes with the SNAI1 transduced cancer proteome of breast adenocarcinoma MCF7 cells and identified 31 proteins that were significantly altered in both RPE and cancer EMT." (PMID 34455105, 2021).
breast ductal carcinoma (3 papers, 2014 to 2020). "Conversely, SNAI1 was found to be elevated in breast ductal carcinoma tissue compared to the other tissue types." (PMID 29352246, 2018).
colitis (3 papers, 2022 to 2023). Inflammation of the colon. "In control animals, Mapk9 mRNA was upregulated in the colon due to the absence of Muc13 expression, whereas the mRNA levels of Mapk1, Mapk9, Rock2 and Snai1 were also affected upon acute colitis in Muc13−/− mice compared to their wildtype counterparts." (PMID 37174625, 2023). "In dextran sulphate sodium (DSS)-induced colitis, it was shown that SNAI1 augmented the effects of MIST1 on the inflammasome protein NLRP3, promoting inflammation." (PMID 35484353, 2022). "SNAI1 has been demonstrated to induce ZEB1 expression and is a potential repressor of E-cadherin and several tight junctions (CLDN1, OCLN, ZO-1) in IECs thereby promoting intestinal barrier dysfunction upon colitis and tumorigenesis in mice." (PMID 37174625, 2023).
cutaneous melanoma (3 papers, 2020 to 2022). A primary melanoma arising from atypical melanocytes in the skin. "Notably, high LOXL3 and SNAI1 or PRRX1 mRNA levels were significantly associated in human cutaneous melanoma patients, unveiling a previously unknown LOXL3–SNAIL1–PRRX1 axis relevant to melanoma biology." (PMID 35267510, 2022). "SNAI1 transcript expression was positively correlated with transcriptome signatures indicative of EMT, stromal, endothelial and cancer associated fibroblasts and inversely correlated with HLA-A transcript expression in our cohort and in the TCGA Skin Cutaneous Melanoma dataset." (PMID 32312968, 2020). "In addition, in 469 samples of skin cutaneous melanomas from the TCGA, a positive correlation was found for LOXL3 gene expression with both SNAI1 and PRRX1 expression (R = 0.4 and R = 0.45, respectively), as well as for PRRX1 with SNAI1 expression (R = 0.45)." (PMID 35267510, 2022).
endometrioid carcinoma (3 papers, 2009 to 2025). "EMT program plays important roles in promoting tumor cell invasion and chemoresistance of endometrioid adenocarcinoma cells via several transcription factors and related pathways, such as SNAIL (SNAI1), and SLUG (SNAI2)." (PMID 27601936, 2016).
endothelial dysfunction (3 papers, 2023 to 2025). In vascular diseases, endothelial dysfunction is a systemic pathological state of the endothelium (the inner lining of blood vessels) and can be broadly defined as an imbalance between vasodilating and vasoconstricting substances produced by (or acting on) the endothelium. "The study revealed the crucial role of LOC100132249/miR-199a-5p/SNAI1 axis in endothelial-to-mesenchymal transition causing endothelial dysfunction." (PMID 39695892, 2024). "The expression of the genes encoding EndoMT transcription factors (SNAI1, SNAI2, TWIST1, and ZEB1), which are generally upregulated at endothelial dysfunction, also showed ≥2-fold increase after PA-BSA treatment, in particular the TWIST1 (≈eight-fold increase) and SNAI1 genes (≈four-fold increase)." (PMID 41465574, 2025).
gastric tumors (3 papers, 2016 to 2021). "The expressions of BRG1 and Snai1 were positively correlated in the gastric tumors of the Gan-mice." (PMID 32071290, 2020). "The levels of FIR family, BRG1, Snai1, FBW7, E-cadherin, c-Myc, cyclin-E, and SAP155 increased in the gastric tumors in FIR+/− mice compared to those expressed in wild-type mice." (PMID 32071290, 2020). "The levels of FIR family (FIR, FIRΔexon2 and PUF60), BRG1, Snai1, FBW7, E-cadherin, c-Myc, cyclin-E, and SAP155 increased in the gastric tumors in FIR+/− mice compared to those expressed in wild-type mice." (PMID 32071290, 2020).
heart failure (3 papers, 2020 to 2024). Inability of the heart to pump blood at an adequate rate to meet tissue metabolic requirements. "The expression of most of the pro-fibrotic and EndoMT mediating genes like CTGF, SNAI1, SNAI2, Twist 1 and 2, BMP4, and Actn1 are upregulated during heart failure and most of these are down-regulated at Week 19 (recovery)." (PMID 33584806, 2020).
kidney cancer (3 papers, 2020). Primary or metastatic malignant neoplasm involving the kidney. "In our study, we first measured the regulatory role of acetate on SNAI1 expression in kidney cancer cell lines 786-O and ACHN." (PMID 32458971, 2020).
medulloblastoma (3 papers, 2018 to 2023). A malignant, invasive embryonal neoplasm arising from the cerebellum. "It has been reported that SHH activation in medulloblastoma cells induces the expression of SNAI1, consequently activating the proto-oncogene N-MYC to induce cellular proliferation and transformation." (PMID 35344158, 2022). "Furthermore, in vitro invasion assays revealed that medulloblastoma cells overexpressing NICD1 are more invasive in Matrigel chambers and express higher levels of SNAI1 and VIM, which are known to be expressed in metastatic cells." (PMID 30297829, 2018).
meningioma (3 papers, 2021 to 2022). A generally slow growing tumor attached to the dura mater. "We noticed that genes such as TGFBI, SNAI1, MMP2, TGFB1, TGFB2, IGFBP7, and LTBP2 were upregulated by the treatment of M2-MDEs in meningioma cells and may contribute to tumor invasion and proliferation behavior." (PMID 35637794, 2022).
metastasis (3 papers, 2022 to 2025). The spread or migration of cancer cells from one part of the body (where they first appeared) to another. "The expression of SNCG was related to the differentiation of OSCC, while that of Snai1 was related to the T stage, lymph node metastasis, clinical stage, and differentiation." (PMID 35434126, 2022).
ovarian tumor (3 papers, 2009 to 2024). "In a different ovarian tumor model where SNAI1 and SNAI2 were also found to be mutually exclusive, SNAI1 was found to bind to E-boxes in the promoter region of SNAI2 and recruit HDAC to repress SNAI2 expression." (PMID 37601651, 2023).
papillary thyroid cancer (3 papers, 2022 to 2025). "SNAI1 and STC1 in papillary thyroid cancer need to be further investigated to determine whether they can be used as predictors to guide the prognosis as well as the treatment of papillary thyroid cancer." (PMID 40295497, 2025).
skin cancer (3 papers, 2020 to 2022). "Initial TGFβ receptor activation in breast or skin cancer results in transcriptional activation of SNAI1, combined with sumoylation of SNAIL at K234 fostering SMAD/SNAIL complex formation that promotes EMT." (PMID 34459003, 2021).
Stroke (3 papers, 2023 to 2024). Sudden impairment of blood flow to a part of the brain due to occlusion or rupture of an artery to the brain. "Notably, increased activity for multiple of these TFs (e.g. Stat5a, Stat3, Myc, Hif1a, Snai1) was also observed in stroke-specific OPC and Oligodendrocyte subsets." (PMID 39043661, 2024). "For instance, MMP-3 KO decreased Snai1 expression to a greater extent in female stroke brains (Log2FC = −1.91, FDR = 1.01e−8) than in male stroke brains (Log2FC = −0.99, FDR = 0.058)." (PMID 39000490, 2024).
acromegaly (2 papers, 2022 to 2024). Acromegaly is an acquired disorder related to excessive production of growth hormone (GH) and characterized by progressive somatic disfigurement (mainly involving the face and extremities) and systemic manifestations. "RORC and SNAI1 expression offered dual and reciprocal information that may help medical treatment decision making in acromegaly, and await full validation with larger series of cases." (PMID 35203668, 2022). "Tumor expression of particular genes was found of prognostic/predictive value in acromegaly patients, These genes include basically CDH1 and SSTR2 but also CDKN1B SNAI2, FLNA, ARRB1, SNAI1 RORC ESRP1, and MKI67." (PMID 39497133, 2024).
acute kidney injury (2 papers, 2022 to 2023). Sudden and sustained deterioration of the kidney function characterized by decreased glomerular filtration rate, increased serum creatinine or oliguria. "And, that IL11 up-regulation in a mouse model of CKD causes renal failure and that anti-IL11 therapy can reactivate endogenous renal repair mechanisms by reversing SNAI1-driven pEMTof TECs to promote kidney regeneration and recovery of function." (PMID 38054591, 2023). "When kidney damage is severe/repeated, TECs undergo SNAI1-driven partial EMT (pEMT) that prevents homeostatic replication and leads to renal failure." (PMID 38054591, 2023). "Mice with acute kidney injury upregulate IL11 in TECs leading to SNAI1 expression and kidney dysfunction, which is not seen in Il11 deleted mice or in mice administered a neutralizing IL11 antibody in either preemptive or treatment modes." (PMID 36470928, 2022).
chondrosarcoma (2 papers, 2017). A malignant cartilaginous matrix-producing mesenchymal neoplasm arising from the bone and soft tissue. "MET‐like phenomena also have been detected in chondrosarcomas where a downregulation of SNAI1/SNAIL led to a gain of mesenchymal markers like E‐cadherin, desmocollin, maspin, and 14‐3‐3σ that in part were regulated epigenetically by cytosine methylation." (PMID 28556516, 2017). "And a MET-like phenomenon in chondrosarcoma was observed through down-regulation of SNAI1." (PMID 28938584, 2017).
Cirrhosis (2 papers, 2016 to 2023). A chronic disorder of the liver in which liver tissue becomes scarred and is partially replaced by regenerative nodules and fibrotic tissue resulting in loss of liver function. "In addition, we examined the expression distribution of SNAI1, ZEB2, and VIM, which are the top three markers exhibiting strong correlation with KLF2, in the GSE25097 dataset related to cirrhosis development." (PMID 37386390, 2023).
hepatoblastoma (2 papers, 2024). Hepatoblastoma (HB) is a malignant hepatic tumor and is the most common pediatric liver cancer. "Increased expression of radixin during epithelial–mesenchymal transition induced by snail family zinc finger 1 (SNAI1) was observed in hepatoblastoma-derived HepG2 cells." (PMID 39457653, 2024).
kidney chromophobe (2 papers, 2020 to 2021). "Levels of SNAI1, which encodes a transcriptional repressor associated with EMT, are correlated positively with the hallmark of EMT in kidney chromophobe carcinoma (Spearman ρ = 0.63, p < 0.001)." (PMID 33299129, 2021).
liver cirrhosis (2 papers, 2012 to 2021). "Further conformation in a different cohort of end-stage COPD lungs and in liver cirrhosis tissues showing that SNAI1, KLF9 and KLF10 are higher expressed in ZZ relative to MM AAT subjects, allows us to propose that the increased expression of zinc finger transcription factors is related to AATD." (PMID 22621770, 2012).
liver steatosis (2 papers, 2018 to 2022). "We verified that transcription factor ISL1 cooperated with demethylase KDM6B to upregulate lipid metabolizing enzyme SNAI1, so as to protect against improve NAFLD, including reducing the degree of hepatic steatosis, plasma lipid concentration, and lipid accumulation in cells." (PMID 35100965, 2022).
localized scleroderma (2 papers, 2020 to 2023). Localized scleroderma is the skin localized form of scleroderma characterized by fibrosis of the skin causing cutaneous plaques or strips. "In addition, immunostainings performed on skin biopsies of patients with morphea, a form of localized scleroderma, suggested the involvement of EMT based on the upregulation of mesenchymal markers such as TGF-β1, α-SMA, fibronectin and SNAI1 and the downregulation of E-cadherin." (PMID 37833928, 2023).
pancreatic adenocarcinoma (2 papers, 2016 to 2019). "Normalized mRNA expression data from TCGA studies of breast, prostate, lung, colorectal and pancreatic adenocarcinomas was downloaded for ZEB1, ZEB2, SNAI1, SNAI2, TWIST1, FOXQ1 and FOXC218,19." (PMID 31780722, 2019).
pharyngeal squamous cell carcinoma (2 papers, 2011). A squamous cell carcinoma that arises from the pharynx. "Immunohistochemistry was used to study the expression of TWIST and SNAI1 in 109 pharyngeal squamous cell carcinomas." (PMID 21834956, 2011). "Elevated nuclear transcription factor expression of TWIST and SNAI1 in tumor stroma may be evidence of ongoing EMT in pharyngeal squamous cell carcinoma." (PMID 21834956, 2011).
prostate tumor (2 papers, 2016 to 2017). "Gene expression of FZD5, DVL3, RELA, MAPK9, CTNNB1, and SNAI1 is higher in metastatic prostate tumors as compared to primary prostate tumors." (PMID 27191743, 2016). "In particular, we found primarily overexpression of CTNNB1, CDH1, SMAD2, SMAD3, TCF3, LEF1 in younger patients and overexpression of SNAI1 and underexpression of KRT5, KRT19, OCLN, CDH2 and MUC1 which clearly indicates different characteristics of prostate tumor in younger vs older patients." (PMID 29206234, 2017). "Compared to the primary prostate tumors, mRNA level of NFKBIA, DUSP6, PLCB3, and SMAD4 are lower in metastatic prostate tumors, while mRNA level of RELA and SNAI1 exhibit opposite trend." (PMID 27191743, 2016).